DLL1 (delta like canonical Notch ligand 1)
Diseases named in the same sentence as DLL1 in open-access papers (continued):
Sharing a sentence is not in itself a finding about the gene and the disease.
Sepsis (continued). "Given the importance of monocytes in host response to infection, it seems plausible that soluble DLL1 could be a plausible early biomarker for detecting sepsis." (PMID 37298115, 2023). "Since the endothelium plays an important role for the recognition of pathogens but also for vascular integrity, DLL1 and other Notch ligands might contribute to the pathological host response during sepsis." (PMID 36834869, 2023). "So far, data on DLL1 for the diagnostics of sepsis are scarce." (PMID 37298115, 2023). "Diagnostic performance was evaluated and showed better performance for DLL1 for the recognition of sepsis (AUC: 0.823; CI 0.731–0.914) than C-reactive protein (AUC 0.758; CI 0.658–0.857), PCT (AUC 0.593; CI 0.474–0.711) and White Blood Cell count (AUC 0.577; CI 0.46–0.694)." (PMID 37298115, 2023). "Moreover, the pathophysiological effect of DLL1 on human monocytes is of particular interest because these cells play a pivotal role in the development of sepsis." (PMID 35922468, 2022). "As it results from a specific process inherent to the syndromes' pathophysiology, the DLL1-Notch axis might serve as a potential theranostic target in sepsis as well." (PMID 31396491, 2019). "Taken together, beside monocytes one might speculate the endothelium as a relevant source of cleaved DLL1 observed in plasma of patients with sepsis as a consequence of signaling." (PMID 31396491, 2019). "Considering the importance of monocytes in the pathophysiology of sepsis, we hypothesized that this mechanism might occur also in the clinical setting and DLL1 might serve as a biomarker of life-threatening bacterial infection." (PMID 31396491, 2019). "However, the release of DLL1 by monocytes in response to a bacterial stimulus and existing retrospective data from clinical cohorts suggest that DLL1 is a promising biomarker for diagnosis of sepsis." (PMID 37298115, 2023). "Therefore, DLL1 could be helpful to support the recognition of sepsis and the consecutive decision on when to start sepsis therapy." (PMID 37298115, 2023). "Therefore, Notch signaling and DLL1 might be an interesting therapeutic target to prevent vascular leakage and severe progression in infectious diseases such as sepsis." (PMID 34955884, 2021). "Also, considering the high amounts of sDLL1 consistently present in patients with sepsis, the value of DLL1 as a biomarker for the identification of bacterial infection in critically ill patients remains unchallenged, with the potential exception of patients after heart transplantation." (PMID 31396491, 2019). "Delta-like canonical Notch ligand-1 (DLL-1), a Notch pathway ligand involved in immune and endothelial signaling, has been shown to reflect disease severity and outcomes in ICU-based sepsis cohorts." (PMID 41973366, 2026). "Soluble host-derived Delta-like Canonical Notch Ligand 1 (DLL1) is a novel, promising and potentially useful biomarker for the diagnosis of sepsis." (PMID 37298115, 2023). "Even though DLL1 has not yet been specifically investigated in this context, the notch signal pathway is of reasonable interest for sepsis research because it modifies T-cell dysfunction and might be associated with sepsis-induced immunosuppression." (PMID 35922468, 2022). "DLL-1 concentrations were significantly higher in patients with sepsis than in those without sepsis (median 11,454 vs. 8,085 pg/mL; p < 0.001)." (PMID 41973366, 2026). "Compared with leucocytes (WBC), C-reactive protein (CRP), or procalcitonin (PCT), a secondary analysis revealed a better discrimination of sepsis from noninfectious systemic inflammatory processes induced by trauma or surgery based on soluble DLL1." (PMID 37298115, 2023). "DLL1 is characterized by a high robustness in non-infectious inflammatory reactions and is therefore also suitable as a biomarker for the diagnosis of sepsis." (PMID 36834869, 2023).
lung carcinoma (10 papers, 2016 to 2025). "PNO1/CRISPR/Cas9 inhibited the expression of Notch1, Notch2, Notch3 Jagged1, and DLL1 in lung cancer A549 and H460 cells." (PMID 36625087, 2023). "Selective activation of DLL1/Notch signaling by multivalent clustered DLL1 induced anti-tumor immune response and suppressed lung cancer growth." (PMID 36008793, 2022). "In addition, former study has indicated that DLL-1 elevates antitumor T-cell immunity and could be used as a target for lung cancer treatment." (PMID 33902591, 2021).
glioblastoma (9 papers, 2011 to 2025). The most malignant astrocytic tumor (WHO grade IV). "Recent studies showed that DLL1 is associated with the CSC activity of glioblastoma and renal cell carcinoma, rhabdomyosarcoma." (PMID 30442981, 2019). "Dll1 has also been implicated in promoting tumor initiating cells/cancer stem cells in multiple cancers such as glioblastoma, renal cell carcinoma, and rhabdomyosarcoma and enhancing T-cell-mediated antitumor immunity." (PMID 30442981, 2019). "On the other hand, DLL1 has also been shown to boost tumor cancer stem cells in renal cell carcinoma and maintain stem cell phenotype in glioblastoma." (PMID 36476410, 2022). "Transcription factors like ASCL1, HES1, OLIG2, SOX2, and NOTCH-ligands (DLL1/3) play crucial roles in GBM plasticity by maintaining a pool of quiescent glioblastoma stem cells (GSCs)." (PMID 40358199, 2025). "Overexpression of DLL1 was identified in choriocarcinoma and hepatocellular carcinoma, while Delta-like 4 (DLL4) expression was correlated to tumor initiation and progression of glioblastoma, poor prognosis in pancreatic cancer and colon cancer." (PMID 28525978, 2017). "However, MGH57 (grade IV glioblastoma) revealed a relatively small subpopulation of malignant cells that do not express OLIG1, OLIG2, DLL1, CCND1, and IGFBPL1, but express ALDOC and ATP1A2." (PMID 33607293, 2021).
adenoma (7 papers, 2013 to 2025). A neoplasm arising from the epithelium. "The expression level of Dll1, Dll3, Jagged1, Jagged2, Notch3, and Hes5 was similar in the small intestine adenomas and the normal tissue epithelium." (PMID 28086833, 2017). "Comparing the adenomas with the normal WT gut we found that Dll1 and Dll3 lose their expression in the large intestine." (PMID 28086833, 2017). "Dll1 demonstrated elevated expression in both residual and untreated adenoma tumors, similar to Stat1 expression." (PMID 23520493, 2013). "Instead, it has been described that other ligands, such as Dll1 and Dll4, were underexpressed in non functioning and prolactin secreting adenomas, and overexpressed in corticotropinomas respectively, pointing to a specific Notch system profile for different pituitary adenomas histotypes." (PMID 28915655, 2017). "Similar findings were made with respect to DLL1 and DLL4 expression, which was significantly increased in FAP duodenal tissue, with the highest expression in FAP adenomas, while only DLL4 correlated significantly with IL-17A(+)NKp44(−)ILC3 frequency." (PMID 40280932, 2025). "Comparatively, in adenomas, ≥2-fold Notch3 expression was detected in 56% followed by Notch1 (44%), Notch4 (33%), and Notch2 (11%), while for ligand Jag1, mRNA was overexpressed in 33%, Jag2, Dll1, and Dll3 in 11%, whereas Dll4 was not expressed in adenomas." (PMID 32211044, 2020). "Previous studies have demonstrated that Dll1, a potential ligand of Notch3, was strongly downregulated in non-functional tumors and in PRL-secreting adenomas." (PMID 23426998, 2013).
breast tumors (5 papers, 2019 to 2023). "The tumor promoting function of DLL1 in ERα+ luminal breast tumors was initiated by estrogen-mediated inhibition of DLL1 ubiquitination and degradation, leading to increase in DLL1 protein stability." (PMID 38269089, 2023). "Knockdown of DLL1 led to decrease in breast tumor volumes and reduced lung metastases, whereas DLL1 overexpression increased the same in vivo." (PMID 38269089, 2023). "Elevated levels of DLL1 in the TME have been shown to suppress EO771 breast tumor growth via CD8+ T cell activation." (PMID 36008793, 2022). "In this study, we found that LNT treatments improved tumor growth inhibition in DLL1-overexpressing EO771 breast tumors." (PMID 36008793, 2022). "Together, these data show that LNT enhanced the inhibitory effect of DLL1 on EO771 breast tumor growth." (PMID 36008793, 2022). "Collectively, these data suggest that quiescent Dll1+ TICs are an important regulator of breast tumor progression and metastasis and are responsible for chemoresistance." (PMID 33462238, 2021). "Our study reveals a central role for the Notch ligand Dll1 in promoting tumor progression, metastasis and chemoresistance in aggressive luminal breast tumors." (PMID 33462238, 2021). "To determine if Dll1+ cells display a TIC phenotype in breast tumors, we performed an in vitro tumorsphere assay to assess the tumorigenic potential of Dll1+ and Dll1− tumor cells isolated from PyMT-Dll1mCh tumors." (PMID 33462238, 2021). "As a consequence, enhanced DLL1-driven Notch signaling serves as a driving force for the initiation, progression, and metastasis of luminal breast tumor." (PMID 30442981, 2019). "We categorized ERα+ luminal patient samples into DLL1high and DLL1low groups on the basis of H-score derived from patient breast tumors stained with DLL1 antibody." (PMID 30442981, 2019). "Therefore, we investigated the effects of LNT on DLL1-mediated tumor growth inhibition in both orthotopic breast tumor and ectopic lung tumor models." (PMID 36008793, 2022). "LNT treatments additively improved the antitumor effects of DLL1 in EO771 breast tumor growth." (PMID 36008793, 2022). "Moreover, DLL1 downregulation caused a 2-fold reduction in the expression levels of CDC25A and SKP2 genes, which are often overexpressed in breast tumors and involved in BC pathogenesis." (PMID 31107884, 2019). "To determine the impact of LNT combined with DLL1 on tumor growth, we firstly evaluated the dose effects of LNT treatments on EO771 breast tumor." (PMID 36008793, 2022).
colon carcinoma (5 papers, 2014 to 2021). "Chromatin immunoprecipitation experiments revealed that Kaiso associates with the DLL1 and JAG1 promoter regions in a methylation-dependent manner in colon carcinoma cell lines, suggesting that these Notch ligands are putative Kaiso target genes." (PMID 28637464, 2017). "Notch1, Dll-1 and Jagged-1 expression were also assessed in stable Kaiso-depleted colon cancer cells and isolated intestinal epithelial cells using real time PCR and western blotting." (PMID 28637464, 2017). "In addition, our results show that miR-34a directly down-regulated MMP9 that seems different from other studies, in which miR-34a indirectly down-regulates MMP9 expression through suppression of Fra-1 in colon cancer and DLL1 in choriocarcinoma." (PMID 25268950, 2014). "Indeed, low levels of the negative Notch regulator miR-34a were associated with a worse response of colon cancer patients to 5-FU, and its overexpression overcame ABCG2-mediated resistance of a stem cell-like subpopulation of colon cancer cells to 5-FU through downregulation of DLL1/Notch signaling." (PMID 34680255, 2021).
ischemia (5 papers, 2009 to 2023). A hypoperfusion of the BLOOD through an organ or tissue caused by a PATHOLOGIC CONSTRICTION or obstruction of its BLOOD VESSELS, or an absence of BLOOD CIRCULATION. "In our study we investigated the role of Dll1 in arteriogenesis and regeneration by using a controlled ischemia model." (PMID 37532879, 2023). "We show that endothelial Dll1 regulates macrophage differentiation and maturation from invading Ly6Chi monocytes, which promotes arteriogenesis and tissue repair after ischemia." (PMID 29038527, 2017). "Our in vivo observations suggested that ischemia generates a transient niche of Dll1 expressed by arterial EC." (PMID 29038527, 2017). "Dll1 is strongly induced in arterial endothelial cells during ischemia-induced arteriogenesis, and Dll1+/- mice display reduced collateral-artery growth and impaired blood-flow recovery after hind-limb ischemia." (PMID 20016694, 2009). "Furthermore, priming of macrophages with Dll1 is critical to obtain pro-angiogenic functions and restore neovascularization and perfusion after ischemia." (PMID 37691936, 2023). "Notch-1 and Dll-1 expression followed ischemia-induced miR-24-3p changes in the muscular microvascular cells, but not in the whole muscles, suggesting that endogenous modulation of miR-24-3p impacts on the regulation of alternative molecular pathways in the non-vascular component of the muscle." (PMID 32138369, 2020).
medulloblastoma (5 papers, 2016 to 2021). A malignant, invasive embryonal neoplasm arising from the cerebellum. "The protein of the DLL1 gene, one of the leading genes in our initial univariate analysis, was detected by IHC in our medulloblastoma tissues." (PMID 34857809, 2021). "DLL1 is a transmembrane ligand of the Notch signaling pathway that is also overexpressed in other types of tumor, such as choriocarcinoma and medulloblastoma, indicating a probable strong involvement of this Notch pathway component in the onset of such tumors." (PMID 28525978, 2017). "For example, miR-34a negatively regulates Delta-like ligand 1 (DLL1) of the Notch pathway and thus down-regulates cell proliferation by inducing apoptosis and neural differentiation in medulloblastoma cells." (PMID 28281638, 2017). "Moreover, miR-34a negatively regulates the Delta-like ligand 1 (DLL1) of the Notch pathway and thus down-regulates cell proliferation by inducing apoptosis and neural differentiation in medulloblastoma cells." (PMID 28073349, 2017). "Both proteins of DLL1 and NCAM1 are detected in medulloblastoma tissues of patients in four subgroups: WNT, SHH, group 3 and group 4." (PMID 34857809, 2021).
osteosarcoma (5 papers, 2009 to 2024). A usually aggressive malignant bone-forming mesenchymal neoplasm, predominantly affecting adolescents and young adults. "MiR-34a-5p enhances multichemoresistance of osteosarcoma by repressing DLL1." (PMID 34733853, 2021). "Delta-like ligand 1 (DLL1) was noted to sensitize osteosarcoma cells to different drugs." (PMID 29036883, 2017). "Although, it was recently reported that DLL1, Notch1, Notch2, and HES1 are expressed in osteosarcoma cell lines, whether expression of Notch signalling molecules in osteosarcoma patient specimens is aberrant has not been clarified." (PMID 19455146, 2009).
choriocarcinoma (4 papers, 2014 to 2019). An aggressive malignant tumor arising from trophoblastic cells. "Other studies implicated DLL1 in choriocarcinoma tumor growth and invasion and in melanoma tumor metastasis." (PMID 31107884, 2019). "miR-34a was also found to reduce cell proliferation and invasiveness partially through its inhibitory effect on Delta-like 1 (DLL1) in choriocarcinoma." (PMID 26077733, 2015).
colorectal cancer (4 papers, 2017 to 2020). A primary or metastatic malignant neoplasm that affects the colon or rectum. "Jag2 was the most frequently observed ligand that was overexpressed in 52%, while a higher expression of Jag1, Dll1, Dll3, and Dll4 was found in 26%, 25%, 25%, and 39% colorectal cancers, respectively." (PMID 32211044, 2020). "Genes of Notch signaling pathway such as Notch1, Notch2, HES1, DLL1, and JAG1 have been reported to be associated with the pathological tumor characteristics and degree of differentiation in colorectal cancer." (PMID 29100272, 2017). "Dll-1 promotes the Wnt and transforming growth factor β (TGF-β) pathways and CTFG gene expression via binding to Smad2/3 and Tof-4, thereby promoting the development of colorectal cancer independent of Notch signaling pathways." (PMID 31198409, 2019).
gastric cancer (4 papers, 2011 to 2022). A primary or metastatic malignant neoplasm involving the stomach. "This is consistent with the research conclusion of Giulia's18, Notch1 activity in gastric cancer is controlled by the epigenetic silencing of the ligand DLL1, and that Notch1 inhibition is associated with the diffuse type of gastric cancer." (PMID 36071128, 2022). "This study shows that Notch1 activity in gastric cancer is controlled by the epigenetic silencing of the ligand DLL1, and that Notch1 inhibition is associated with the diffuse type of gastric cancer." (PMID 22249198, 2011). "Our results provide evidence that Notch1 activation in GC is controlled by the epigenetic silencing of the ligand DLL1, and that Notch1 inhibition is associated with the diffuse type of gastric cancer." (PMID 22249198, 2011). "On the other hand, from an ING-GAS mouse model infected with H. pylori, it was revealed that methylation silencing of Dll1 has the ability to control Notch1 activity in gastric cancer." (PMID 28881855, 2017). "Collectively, the Dll1-Notch1 signaling axis and the target gene Hes1 are suggested to have important roles in gastric cancer." (PMID 28881855, 2017). "With samples from 52 patients with gastric carcinoma and 21 healthy controls, it was revealed that the expression of Dll1 is correlated with Hes1 expression." (PMID 28881855, 2017). "This is consistent with published findings that DLL1 controls Notch 1 activity in mouse intestinal tissue and Notch 1 activation in patients with intestinal-type of gastric cancer." (PMID 22249198, 2011). "For this purpose, we evaluated the Notch1 cascade in gastric cancer cell lines and we found a specific correlation between DLL1 expression and promoter hypermethylation." (PMID 22249198, 2011). "In contrast, in the diffuse type of GC, DLL1 epigenetic silencing represses the activation of Notch and is associated with high level of HATH1, which is a specific feature of diffuse of mixed type of gastric cancer." (PMID 22249198, 2011). "In GC patients, we found a correlation between DLL1 and Hes1 expression, while DLL1 methylation and Hath1 expression were associated with the diffuse and mixed type of gastric cancer." (PMID 22249198, 2011). "A study undertaken by Piazzi and colleagues to assess the role of Notch1 and the corresponding ligand Dll1 in gastric carcinoma shows that Dll1 is not detected in KATOIII, SNU601, SNU719 and AGS cells from eight different types of gastric cancer cell lines." (PMID 28881855, 2017).
leukemia (4 papers, 2013 to 2023). A malignant (clonal) hematologic disorder, involving hematopoietic stem cells and characterized by the presence of primitive or atypical myeloid or lymphoid cells in the bone marrow and the blood. "Then, it is proved that adipocytes attract T‐ALL cells by releasing CXCL13 and support leukemia cell survival by activating the Notch1 signaling pathway via DLL1 and Notch1 binding." (PMID 37072664, 2023). "QRT-PCR analysis demonstrated that miR-195-5p was down-regulated, and DLL1 was up-regulated in the MDS/leukemia cell lines." (PMID 27571714, 2016). "For instance, we measured decreased Jagged-1 and DLL1 levels in leukemia cells from responsive PDX following Givinostat administration." (PMID 26764573, 2016). "In contrast, Notch1 and Notch2 genes were un-methylated in any of the leukemia cell lines and normal controls, while DLL1, DLL3, DLL4 and Hes6 showed only low levels of methylation (9–27%) in these leukemia cell lines." (PMID 23637910, 2013). "We screened miR-195-5p and DLL1 expression in several MDS/leukemia cell lines." (PMID 27571714, 2016). "The results showed that leukemia burden decreased after the treatment of DEX, but the expression levels of DLL1 in adipocytes and the levels of Notch1 in T‐ALL cells around adipocytes were higher." (PMID 37072664, 2023).